CASP1 (caspase 1)
Diseases named in the same sentence as CASP1 in open-access papers (continued):
Sharing a sentence is not in itself a finding about the gene and the disease.
Alzheimer disease (continued). "In the context of neurological diseases, caspase-1 has a deleterious role in the disease progression since caspase-1 knockout mice were protected from clinical hallmarks of Alzheimer’s disease." (PMID 31892810, 2019). "For example, the activation of caspase-1 promoted neuronal injury in experimental models of Alzheimer’s disease." (PMID 29357878, 2018). "Here, the authors investigate the therapeutic potential of a Caspase-1 inhibitor in a mouse model of Alzheimer’s disease." (PMID 30254377, 2018). "Caspase-1 and IL-18 have also been shown to be produced in neurodegenerative diseases such as Alzheimer's disease and Multiple sclerosis." (PMID 28861067, 2017). "Neuroinflammation can also elicit activation of inflammasome and caspase-1 in the brains of patients with Alzheimer disease." (PMID 26218286, 2015). "Caspases are proteases involved in apoptosis and inflammation, and CASP‐1 is particularly well known as a major component of the NLRP3‐CASP1 inflammasome and a promising therapeutic target for Hutchinson‐Gilford progeria, another premature aging syndrome, and Alzheimer's disease." (PMID 41078088, 2025). "However, there is evidence that CASP1 is overexpressed in the frontal cortex and hippocampus of patients with Alzheimer's disease." (PMID 41078088, 2025). "Human caspase-1 in particular carriesout the transformation of the pro-inflammatory cytokine pro-interleukin-1βinto its active form, a key process in the inflammatory response andthen in many diseases, such as Alzheimer’s disease." (PMID 37066044, 2023). "This study aimed to explore the mechanism of action of caspase-1/IL-1β in Alzheimer's disease." (PMID 33509083, 2021). "Caspase-1/IL-1β participates in the development of Alzheimer's disease." (PMID 33509083, 2021). "Thus, we used AC-YVAD-CMK to inhibit activity of caspase-1/IL-1β to further explore the mechanism of action of caspase-1/IL-1β in the pathogenesis of Alzheimer's disease." (PMID 33509083, 2021). "Interestingly, caspase 1 and sialophorin are differentially expressed in the opposite direction after the intake of supplements compared to Alzheimer’s disease patients." (PMID 33302351, 2020). "NLRP3/caspase-1 axis played a central role in the pathogenesis of Alzheimer's disease." (PMID 26924896, 2016). "They exert beneficial effects in vivo in models of Parkinson's, Huntington's and Alzheimer's diseases, by inhibiting caspase-1, caspase-3, inducible nitric oxide synthase expression and nitric oxide-mediated toxicity, although a role of their anti-fibrillogenic efficacy cannot be ruled out." (PMID 18365024, 2008). "Thus, our research provides a theoretical basis for the pathogenesis of Alzheimer's disease, and caspase-1/IL-1β may be a target for Alzheimer's disease treatment." (PMID 33509083, 2021). "Moreover, caspase-1 is involved in the pathogenesis of several diseases, including periodontal disease, Alzheimer’s disease, cardiovascular disease, rheumatoid arthritis, endometriosis, and Crohn’s disease, all of which are characterised by cell death and inflammation." (PMID 35008798, 2021). "Thus, this article aimed to explore whether caspase-1/IL-1β can affect GluA1 membrane transport by regulating the interaction between Stargazin and GluA1 in Alzheimer's disease." (PMID 33509083, 2021). "Thus, caspase-1 may be an important molecular target for neuroprotection and intervention therapy for Alzheimer's disease." (PMID 33509083, 2021). "In models of Alzheimer’s disease, MCC950 effectively dampens the inflammasome activation triggered by Aβ or tau, preventing the cleavage and release of caspase-1 and IL-1β." (PMID 40260242, 2025). "In Alzheimer’s disease, the NLRP3 inflammasome assembles inside of microglia upon activation, leading to increased cleavage and activity of caspase-1, resulting in neurodegeneration and cognitive decline." (PMID 38645501, 2024). "Thus, caspase-1/IL-1β may be a target for Alzheimer's disease treatment." (PMID 33509083, 2021).
Alzheimer disease (continued). "Evidence of its involvement in early Alzheimer’s disease includes enhanced cerebral expression of the key NLRP3 component, active caspase-1." (PMID 34188184, 2021). "Chronic cerebral hypoperfusion accelerates Alzheimer's disease by enhancing NLRP3 inflammasome, and activating caspase-1 and IL-1β in hippocampus and thalamus of mice." (PMID 33509083, 2021). "This may help explain the recent unexpected finding that pharmacological CASP‐1 inhibitors protect against cognitive decline in mouse models of Alzheimer dementia by altering neuronal function rather than modulating inflammation." (PMID 41078088, 2025). "In Alzheimer’s disease, the characteristic accumulation of β-amyloid peptide may induce neuroinflammation through P2X7 receptor mobilization and subsequent activation of NLRP3/caspase-1 pathway." (PMID 37114062, 2023). "Considering the non-negligible role of NLRP3/ASC/caspase-1 axis-mediated inflammation in Alzheimer’s disease, Alzheimer’s disease transgenic mice with selective suppression of NLRP3 inflammasome or caspase-1 expressions in the brain revealed significantly improvement cognitive functions." (PMID 36009120, 2022). "However, the biological role of caspase-1/IL-1β in Alzheimer's disease has not been fully elucidated." (PMID 33509083, 2021). "However, whether caspase-1 can regulate membrane transport disorder of AMPA receptors in Alzheimer's disease has not been reported yet." (PMID 33509083, 2021).
Arthritis (43 papers, 2006 to 2025). Inflammation of a joint. "Deletion of the Pycard gene (encoding ASC) protected CIA mice from developing arthritis and bone erosion showing the importance of canonical inflammasomes; however, Nlrp3 and Casp1 null mice developed comparable disease to WT mice." (PMID 35567665, 2022). "Neutrophil-derived proteases, including NE or cathepsins, have been implicated in caspase-1 independent pro-IL-1β processing in arthritis and Pseudomonas aeruginosa infection mouse models." (PMID 29228045, 2017). "Therefore, the anti-inflammatory effect of osteostatin in the gouty arthritis model would be, in part, associated with the inhibition of caspase-1 activation induced by MSU crystals." (PMID 38474000, 2024). "Indeed, during arthritis-induced sterile inflammation, caspase-1-independent processing of IL-1β leads to disease-associated inflammation as a result of neutrophil recruitment and proteinase 3, while P. aeruginosa infections of the cornea require neutrophil elastase." (PMID 25198773, 2014). "Genetic ablation of Ncoa6 substantially attenuated the severity of FA-induced ATN and MSU crystal-induced arthritis in mice and decreased IL-1β and active caspase-1 levels." (PMID 38195836, 2024). "MiRNA-20a targets TXNIP to inhibit the activation of NLRP3, ASC and caspase-1 in adjuvant-induced arthritis FLS and to suppress the secretion of IL-1 and MMP-1." (PMID 37426634, 2023). "The levels of NLRP3, ASC, and caspase-1 increased in both arthritic rats and patients with arthritis." (PMID 36619197, 2022). "In animal investigations, inhibition of NLRP3 and caspase-1 was also found to be useful in alleviating the symptoms of arthritis in RA (CIA mouse model)." (PMID 36532040, 2022). "Expression of NLRP3, caspase-1, and IL-1 is increased in the synovial tissues of CIA mice, and IL-1α, IL-1β, and IL-1αβ-deficient mice are less sensitive to CIA-induced arthritis." (PMID 35628185, 2022). "ASC knockout (ASC-/-) mice are protected from arthritis, while caspase-1 knockout (caspase-1-/-) and NLRP3 knockout (NLRP3-/-) mice are susceptible to CIA." (PMID 35095918, 2021). "NLRP1 mutations have been reported to increase systemic amounts of caspase-1 in patients with arthritis and dyskeratosis; our results are consistent with these findings." (PMID 32695183, 2020). "The dual blockage of both caspase-1 and proteinase 3 is seen as a potential anti-inflammatory therapeutic option in a murine model of arthritis." (PMID 30583612, 2018). "We have selected gambogic acid as a promising therapeutic candidate for the inhibition of both IL-1β and TNF secretion, due to the reduction in caspase-1 and NF-κB activation, and consequently for the treatment of arthritis." (PMID 24623960, 2014). "In contrast to caspase-1 and NLRP3 deficient mice, ASC deficient mice were completely protected from the development of arthritis in a collagen induced arthritis study." (PMID 22216309, 2011). "Furthermore, in vivo studies also showed that PR3 and elastase can compensate caspase-1 absence for pro-IL-1β processing both in a serum transfer–induced arthritis model and in the monosodium urate monohydrate crystal–induced peritonitis model." (PMID 36091026, 2022). "Mice lacking NLRP3 or caspase-1 have reduced joint lesions with spontaneous HA deposition in a progressive ankylosis-deficient model of arthritis." (PMID 35628185, 2022). "Taking the two possible mechanisms together, caspase-1 activation by statins may aggravate arthritis by inducing IL-1β and IL-18." (PMID 22537858, 2012). "Another possible mechanism by which statins may affect arthritis is through their induction of caspase-1, IL-1β, and IL-18 in monocytes, resulting in increased IFNγ production by T cells." (PMID 22537858, 2012). "Increased secretion of NLRP3, ASC, and caspase-1 has been reported in arthritis patients, and suppression of NLRP3 activity was reported to suppress arthritis in rat models." (PMID 36619197, 2022).
Arthritis (continued). "Two studies of antigen-induced murine arthritis show dependence on ASC, but caspase-1, NLRP3, and NLRC4 independence." (PMID 32366256, 2020). "These functions suggest a protective role for STAT-1 in arthritis, and this role is supported by elevated expression of the STAT-1 pro-apoptotic target gene caspase-1 in RA synovium." (PMID 16507120, 2006). "It is reported that NOD-like receptor thermal protein domain associated protein 3 (NLRP3) inflammasome triggered by TGR5-cAMP-PKA axis play a direct role in arthritis inflammation, we therefore further determined the levels of NLRP3, ASC, caspase-1 p20, and IL-1β p17." (PMID 40375326, 2025). "In the present study, the mRNA level of caspase-1 in NLRP3 inflammasome was significantly downregulated in Stefin B-overexpressed GA mice, accompanied by a decreased serum IL-17 level, which is closely correlated to arthritis." (PMID 38294507, 2024). "ASC deficiency suppresses arthritis in RA model mice through reduced T cell priming, which is independent of NLRP3 or caspase-1." (PMID 35628185, 2022). "ASC by itself, independent of caspase-1, can induce autoimmune diseases including arthritis and encephalitis." (PMID 28430665, 2017). "Because the activation of the NLRP3 inflammasome could induce the overproduction of IL-1β, resulting in inflammation and arthritis, we evaluated the expression of NLRP3, caspase-1 p20 (a functional caspase-1 subunit) and IL-1β in the ankle joint synovial tissue by Western blot." (PMID 34583676, 2021). "Importantly, wedelolactone could abate MSU‐induced IL‐1β production and neutrophils migration into peritoneal cavity, and reduced caspase 1 (p20) and IL‐1β expression in the joint tissue of MSU‐induced arthritis." (PMID 32656909, 2020).
Cerebral ischemia (41 papers, 2016 to 2026). Restriction of arterial blood supply to the brain associated with insufficient oxygenation to support the metabolic requirements of the tissue. "And Caspase-1 was found to play a vital role in regulating inflammation pathways and pyroptosis in many inflammation-associated diseases, especially in cerebral ischemia-reperfusion injury." (PMID 35193116, 2022). "Pyroptosis is activated in cerebral ischemia/reperfusion injury, which activated CASP1 to form Gasdermin D pore and thus cause cell swelling and the release of inflammatory factors." (PMID 34493232, 2021). "This study confirmed that quercetin can directly bind to the NLRP3 protein and alleviate cerebral ischemia-induced inflammatory injury by inhibiting the activation of the NLRP3/Caspase-1/GSDMD pyroptosis axis and the release of downstream inflammatory factors." (PMID 41892344, 2026). "Pyroptosis is mediated by the activation of caspase-1, triggered by the formation of inflammasomes in response to cerebral ischemia." (PMID 38540725, 2024). "In the Western blot and immunofluorescence analyses, the expression levels of pyroptosis-related factors, such as NF-κB, NLRP3, GSDMD, ASC, Caspase-1, and IL-1β, were increased significantly after cerebral ischemia-reperfusion injury." (PMID 39199474, 2024). "The NF-κB/NLRP3/Caspase-1/GSDMD pathway is involved in cerebral ischemia-reperfusion injury, and its related molecules have become experimental targets for alleviating cerebral ischemia-reperfusion injury." (PMID 39199474, 2024). "Inhibition of pyroptosis components caspase-1, inflammasomes and gasdermin has been proved to confer protection in cerebral ischemia, AD, PD, developmental white matter injury and EAE." (PMID 36803990, 2023). "The antiepileptic drug valproic acid (VPA) was also reported to improve cerebral ischemia/reperfusion injury via modulating an apoptosis repressor with caspase recruitment domain (ARC)-mediated caspase-1-dependent pyroptosis pathway." (PMID 37332874, 2023). "The classical pyroptotic pathway is mediated by caapase-1, and the role of caspase-1 in cerebral ischemia has been revealed, and knockout of caspase-1 or the use of caspase-1 inhibitors has a long-term neuroprotective effect on cerebral ischemic injury." (PMID 37373274, 2023). "ROS, NLRP3, Caspase-1, and IL-1β expression increased after cerebral ischemia, and this was reversed by HS treatment." (PMID 37371417, 2023). "Western blotting revealed that, in comparison with Sham group, the expression of the main components of NLRP3 inflammasome, NLRP3, ASC, and cleaved caspase-1 were enhanced by cerebral ischemia-reperfusion injury." (PMID 37650573, 2023). "Considered together, these results suggest that HS can downregulate the production of ROS and the expression of NLRP3, Caspase-1, and IL-1βin the peri-infarction cortex after cerebral ischemia." (PMID 37371417, 2023). "These activated inflammatory bodies activate caspase-1 and induce pyroptosis, which aggravates cerebral ischemia/reperfusion injury (Chavarría-Smith and Vance, 2015)." (PMID 35600074, 2022). "In summary, EA plays a neuroprotective role by reducing the pyroptotic neurons that were caspase 1-mediated and inflammatory response after cerebral ischemia–reperfusion." (PMID 35600074, 2022). "The occurrence of pyroptosis relies on caspase-1/4/5/11, and caspase-1 and caspase-11 are the main activated inflammatory caspases during cerebral ischemia." (PMID 35600078, 2022). "In the I/R group, the positive rate of TUNEL and caspase-1 double-stained neurons in C57 mice significantly increased, which suggested that pyroptosis was involved in cerebral ischemia/reperfusion injury." (PMID 35600074, 2022). "Studies have shown that pharmacological inhibition of caspase-1 reduces ischemic neuronal damage and functional decline after cerebral ischemia." (PMID 36441377, 2022).
Cerebral ischemia (continued). "The cerebral ischemia–reperfusion injury model of C57 and caspase-1 gene knockout (Cas-1 ko) mice was established by Longa's method." (PMID 35600074, 2022). "The protein expression of NLRP3, ASC, and CASP1 were significantly increased after cerebral ischemia (p < 0.01)." (PMID 36091745, 2022). "Not only that, Caspase-1 inhibitors have been shown to reduce the damage of cerebral ischemia-reperfusion injury by inhibiting inflammation and pyroptosis." (PMID 35193116, 2022). "IL-1β, caspase-1, and inflammasomes have been reported to play important roles in cerebral ischemia reperfusion injury." (PMID 33747105, 2021). "We using NLRP3 shRNA or QNDP found that QNDP or QNDP and sh-NLRP3 obviously inhibited the levels of NLRP3, ASC and cleaved-caspase 1, then to regulate the inflammatory cytokines and inhibit apoptosis in cerebral ischemia in vivo and in vitro." (PMID 32153398, 2020). "The pathogenic role of LPA1 in cerebral ischemia was associated with NLRP3 inflammasome activation, including NLRP3 upregulation, ASC speck formation, caspase-1 activation, and IL-1β maturation in a post-ischemic brain." (PMID 33202644, 2020). "Pharmacological inhibition of caspase-1 activity protected neuronal death induced by brain ischemia or trophic factor withdrawal." (PMID 31127201, 2020). "The mechanism may be downregulation of NFΚB/NLRP3/Caspase-1/GSDMD pathway protein expression and regulation of NLRP3 inflammasome-mediated pyroptosis associated with cerebral ischemia-reperfusion." (PMID 39199474, 2024). "This combination may alleviate cerebral ischemia-reperfusion injury in rats by downregulating the signaling molecules of the NF-κB/NLRP3/Caspase-1/GSDMD pathway." (PMID 39199474, 2024). "Additionally, GSDMD, as an important factor of pyroptotic death execution downstream of Caspase-1 (canonical inflammasome), directly participates in brain ischemia-reperfusion injury." (PMID 39199474, 2024). "Concurrently, the anti-inflammatory property of CEP enables its use in the treatment of cerebral ischemia/reperfusion injury, wherein CEP inhibits NLRP3 signaling, and caspase-1, thereby suppressing the overproduction of IL-1β and IL-18, thus attenuating cerebral ischemia/reperfusion injury." (PMID 36677811, 2023). "It was reported that NLRP3/caspase-1-dependent pyroptosis participated in the cerebral ischemia/reperfusion injury and cognitive decline after focal cortical infarction, NLRP3 inhibitor and caspase-1 inhibitor could improve the symptoms, respectively." (PMID 37332874, 2023). "In addition, the inhibition of CASP1 has proven to relieve cerebral ischemia in a murine model by targeting the canonical inflammasome pathway of pyroptosis that is important for neuronal death in acute IS." (PMID 36466169, 2022). "Interestingly, miR-124 upregulation plays a protective role in cerebral ischemia–reperfusion injury by restricting pyroptosis as evidenced by the limited expressions of IL‐1β, IL‐18, Caspase-1, and GSDMD." (PMID 36243708, 2022). "This study demonstrated that downregulated XBP-1 could inhibit pyroptosis by inhibiting the NLRP3/Caspase-1/GSDMD pathway in the hippocampus which rescues cerebral ischemia/reperfusion injury." (PMID 35497095, 2022). "In our present study, QNDP could reduce the expression of NLRP3, cleaved caspase-1, IL-1β, and IL-18, alleviate brain edema, and improve the neurological function after cerebral ischemia." (PMID 32153398, 2020). "Cerebral ischemia and abnormal glucose level can both activate inflammasome and recruit simultaneously a variety of immune cells which mediate the activation of proinflammatory cytokine caspase-1 and IL-1β." (PMID 29853850, 2018). "Inhibition and deficiency of caspase-1 or nod-like receptor family, pyrin domain containing 3 (NLRP3) inflammasome have shown benefits in regulating inflammation and outcomes in AD, experimental autoimmune encephalomyelitis (EAE), TBI, brain ischemia and Parkinson disease (PD)." (PMID 36803990, 2023).